SDR9C7 (short chain dehydrogenase/reductase family 9C member 7)
Description:
Plays a crucial role in the formation of the epidermal permeability barrier. Catalyzes the NAD+-dependent dehydrogenation of the linoleate 9,10-trans-epoxy-11E-13-alcohol esterified in omega-O-acylceramides (such as in N-[omega-(9R,10R)- epoxy-(13R)-hydroxy-(11E)-octadecenoyloxy]-acylsphing-4E-enine) to the corresponding 13-ketone, the reactive moiety required for binding of epidermal ceramides to proteins. Displays weak conversion of all-trans-retinal to all-trans-retinol in the presence of NADH. Has apparently no steroid dehydrogenase activity.
Synonyms: SDR-O; RDHS; SDRO; ARCI13
Tractability: No criterion of Open Targets' tractability assessment is met for any kind of drug.
Gene: Protein-coding gene on chromosome 12 (56,923,133 to 56,934,408, reverse strand). Ensembl gene ENSG00000170426.
Subcellular location: Cytoplasm
Pathways (Reactome):
Sensory Perception: The canonical retinoid cycle in rods (twilight vision)
Gene Ontology:
Molecular function: all-trans-retinol dehydrogenase (NAD+) activity; oxidoreductase activity, acting on the CH-OH group of donors, NAD or NADP as acceptor
Biological process: retinol metabolic process
Cellular component: cytoplasm
Genetic constraint (gnomAD): Loss-of-function variants: 14 observed, 25.94 expected, observed/expected ratio (o/e) 0.54, 90% interval 0.35 to 0.84. The upper end of that interval is the gene's LOEUF score, 0.84, which puts it in group 3 of 6, group 1 being the genes least tolerant of losing a copy. Missense variants: 381 observed, 423.19 expected, observed/expected ratio (o/e) 0.9, 90% interval 0.83 to 0.98. Synonymous variants: 166 observed, 162.87 expected, observed/expected ratio (o/e) 1.02, 90% interval 0.9 to 1.16.
Homologues: Orthologues: chimpanzee SDR9C7 (99% identical), macaque SDR9C7 (96% identical), pig SDR9C7 (92% identical), dog SDR9C7 (89% identical), rabbit SDR9C7 (87% identical), rat Sdr9c7 (87% identical), guinea pig SDR9C7 (85% identical), mouse Sdr9c7 (85% identical). Paralogues in human: RDH16 (52% identical), HSD17B6 (51% identical), RDH5 (48% identical), DHRS9 (44% identical), BDH1 (34% identical), HSD17B2 (32% identical), HSD11B2 (29% identical), HSD17B1 (25% identical), RDH12 (24% identical), RDH11 (24% identical), RDH10 (23% identical), SDR16C5 (23% identical), and 13 more.
Diseases named in the same sentence as SDR9C7 in open-access papers:
SDR9C7 is named in the same sentence as 8 diseases in open-access papers, as found by Europe PMC text mining. Sharing a sentence is not in itself a finding about the gene and the disease. The quoted sentences say what the papers report.
ichthyosis (2 papers, 2019 to 2020). Disorders of cornification that are characterized by visible scaling and/or hyperkeratosis of most or all of the skin. "Mutations in SDR9C7, encoding a short-chain dehydrogenase/reductase family 9C member 7 (SDR9C7), have been recently found in ichthyosis." (PMID 32054030, 2020).
esophageal squamous cell carcinoma (1 paper, 2019). Esophageal squamous cell carcinoma (ESCC) is a type of esophageal carcinoma (EC) that can affect any part of the esophagus, but is usually located in the upper or middle third. "SDR9C7 promotes lymph node metastasis in esophageal squamous cell carcinoma." (PMID 30704450, 2019).
SDR9C7 also shares sentences with these, for which no sentence is quoted: autosomal recessive congenital ichthyosis (1 paper); Hyperkeratosis (1); hyperlipidaemia (1); Leber congenital amaurosis (1); retinal diseases (1); tumour (1).